IL18 (interleukin 18)
Diseases named in the same sentence as IL18 in open-access papers (continued):
Sharing a sentence is not in itself a finding about the gene and the disease.
infection (continued). "The concentration of IL-18 measured in the serum of TLR2−/− mice was significantly reduced when compared to wild-type mice following infection, and this was not due to differences in the expression of IL-18 mRNA (data not shown)." (PMID 21698237, 2011). "Surprisingly, Asc-/- mice, which should be equivalent to DKO because of the absence of IL-1β or IL-18, survived the infection." (PMID 22241982, 2011). "In conclusion, we have shown that various TLR agonists and infection with Salmonella can induce IL-23, IL-18 and IL-1β, but not IL-12, production in monocytes and Mφ1." (PMID 20027291, 2009). "Furthermore, infection of THP-1 cells with vMyxM013-KO virus induced the activation of caspase-1 and processing and secretion of pro-inflammatory cytokines IL-1β and IL-18." (PMID 19851467, 2009). "Thus, while IL-12 appeared dispensable for NK cell activation in response to infection with HSV-1, these data demonstrated a role for IL-18 in the immediate and transient production of IFN-γ by NK cells following HSV-1 infection in vivo." (PMID 17407097, 2007). "However, both IFN-λ3, and IL-18 were barely produced in primary IECs from mouse intestinal organoids of both wild-type Trim29fl/fl and Trim29IEC-KO mice without infection." (PMID 39396665, 2025). "During this phase of infection, when levels of pro-inflammatory cytokines (such as IL-18) are low, secreted ISG15 from infected epithelial cells can help NK cells to increase secreted IFN-γ levels, thereby enabling an earlier and more rapid response to the infection." (PMID 40627782, 2025). "We found that both parent H1N1 and H1N1-E158A viruses induced cardiac IFNβ, TNF, IL-6, IL-18, and IL-1β above levels seen in mock control animals and that the H1N1-E158A virus induced higher levels of each inflammatory cytokine than the parent virus at day 5 post infection." (PMID 40909698, 2025). "Infection with MHV-68 resulted in an elevated abundance of cytokines (TNF-α and IL-6) that triggered inflammation, an upsurge in pyroptosis-related molecules involving caspase-1, IL-1β, and IL-18, along with a decrease in IL-10 concentration, an anti-inflammatory cytokine, in peritoneal macrophages." (PMID 40041420, 2025). "Clearance of infection by S. Typhimurium and S. Enteritidis from the intestinal tract of infected chickens was also shown to be due to a Th1-dominated response involving increased expression of IFN-γ mRNA in the gut and deeper tissues and generation of IL-12 and IL-18 early in infection." (PMID 38543472, 2024). "Compared to the non-infection group, we observed elevated levels of the majority of measured cytokines (25/48) in the CSF during Mtb infection, including TNF-α, IFN-γ, IL-1β, IL-2, IL-3, IL-6, IL-8, IL-10, IL-12(p40), IL-17A, IL-18, IP-10, MIG, MCP-3, MIP-1α, and MIP-1β." (PMID 38047697, 2024). "Extracellular MRP8/14, which is a heterodimeric complex released by phagocytes during infection, acts as an endogenous alarmin that amplifies the TLR4 signaling-dependent inflammatory response by inducing proinflammatory cytokines, such as TNF-α, IL-1β, IL-12 and IL-18." (PMID 37701855, 2023). "Interestingly, IL-18 levels accumulated at day 10 and day 24 post-infection (p<0.05 and 0.01, respectively) and viremic mice harboured higher IL-18 levels than non-viremic mice (p<0.001)." (PMID 36800238, 2023). "Notably, IL-33, TGFα, and IL-18 were depleted in end of infection samples compared with the negative controls, indicating a difference in cytokine profile between resolving infection and baseline innate immune status." (PMID 36586415, 2023). "In contrast, elevation of inflammatory IL-6 and IL-18 was independent of time of infection." (PMID 37490342, 2023).
infection (continued). "Similar to WT STm infection, genes involved in the regulation of immune responses (ATF3, BATF3, ETS2, IRF9, NFκB2, MAFA, TNFAIP3), effector functions, (CCL4, CD200L, CD40, CD72, CD80, IL18) and TLR signaling, (EAF2, TLR15, TRAF3IP2, TOLLIP) were upregulated after ΔprgH STm infection in both models." (PMID 37854334, 2023). "Indeed, we observed that the most considerable augmentation of pro-inflammatory IL-1β, IL-6, IL-15, IL-18, IFN-γ, eotaxin, GRO-α, IP-10, MCP-1, MIP-1α, MIP-1β, and regulatory IL-1RA, occurred at the terminal stage of the disease (7 days post-infection) in our rhesus macaques." (PMID 38035334, 2023). "The present study investigated whether SaaS mediated the secretion of cytokines in vivo, with the interleukin (IL)-1β, IL-6, IL-18, tumor necrosis factor-α (TNF-α), inducible nitric oxide synthase (iNOS) and cyclooxygenase-2 (COX-2) levels in colon after infection examined with ELISA or RT-qPCR." (PMID 37158502, 2023). "Interestingly, the inflammasome-regulated cytokine IL-18 (but not IL-1ß) was significantly increased in ARDS patients who developed pulmonary superinfections compared to patients without a secondary infection (p = 0.0271)." (PMID 37297845, 2023). "Moreover, in contrast to our observations in uninfected mice, whole colon lysates of C. rodentium-infected mice showed the presence of mature IL-18 as well as cleaved caspase-1 and GSDMD, indicating that this infection induced inflammasome activation in the colon." (PMID 38090573, 2023). "Furthermore, when measuring biomarkers of inflammation during active infection, analyses with area under the curve (AUC) values above 0.75 indicated that caspase-1, ASC, IL-1β and IL-18 are reliable biomarkers of the inflammatory response during active COVID-19 infection." (PMID 37168848, 2023). "Furthermore, in the absence of infection or other treatment, active SpeB alone was sufficient to activate IL-18 in a dose-dependent manner." (PMID 37068092, 2023). "Furthermore, no significant release of the inflammasome-regulated cytokine IL-1β was observed in the absence of infection, consistent with inflammasome-independent secretion of pro-IL-18." (PMID 37068092, 2023). "Simultaneous knockdown of caspase-1 and caspase-8 still allowed for the release of IL-18 during Δ6 Yptb infection, suggesting that they are unlikely to play overlapping roles and may act sequentially." (PMID 37615436, 2023). "In line with our in vivo results and regardless of strain genetic background, infection with ∆T mutant strains resulted in significantly higher levels of IL-1β and IL-18 secreted by BMDMs, and complementing ∆T strains with pExoT reduced the production of these pro-inflammatory cytokines." (PMID 35277504, 2022). "IL-18 is instead a potent IFN-γ inducer, able to activate T cells and NK cells in synergy with IL-12, thus its secretion in response to infection with attenuated NH/P68 might promote the development of ASFV-specific T cell responses, limiting virus spread into the host, as we previously speculated." (PMID 36298767, 2022). "However, IL-18 of epithelial and immune cell origin has no protective effect against intestinal STm infection." (PMID 35216425, 2022). "Upon infection, cardiac-resident cells, such as cardiomyocytes, endothelial cells, and fibroblasts, may contribute to acute inflammation by secreting cytokines such as IL-1β, IL-6, TNF-α, and IL-18." (PMID 34504807, 2021). "Once again, we did not detect any noticeable difference in the expression of these receptors between wild-type and Il18r1-/- mice post LPS infection, indicating that NK cells can upregulate the expression of nutrient transporters in the absence of IL-18 signaling during in vivo inflammation." (PMID 34093543, 2021). "In addition, the levels of secreted IL-1β and IL-18 in the culture media remained at the basal level which did not change through the course of infection." (PMID 33796483, 2021).
infection (continued). "In senescence-related susceptible individuals exposed to endogenous (genetics and epigenetics) stress and exogenous (environment and infection) injury, virus-induced NLRP3 inflammasome activation may drive the inflammation response by activating caspase-1 and production of mature IL-1β and IL-18." (PMID 34638790, 2021). "However, infection of ΔNLRP3, Δcaspase-1, and ΔASC cells resulted in minimal production of IL-18 not significantly different from mock infection." (PMID 32101570, 2020). "In contrast, in vivo infection in mice leads to significant secretion of IL-18 but not IL-1β24." (PMID 32753607, 2020). "Therefore, we examined IL-18 production in THP-1 cells at 4 and 8 hours post-infection with HSV-1." (PMID 32101570, 2020). "Similarly, IL2C pretreatment significantly increased systemic IFN-γ levels in the serum after i.v. infection but, as expected, did not lead to a significant change in the levels of serum IL-18." (PMID 32753607, 2020). "The cleaved/activated Caspase-1, cleaved/activated IL-1β, and IL-18 were significantly induced in human corneal epithelial cells following infection with virulent laboratory strains of HSV-1, McKrae and 17, as early as 2 h post-infection, compared to control β-actin (P < 0.05)." (PMID 31367214, 2019). "However, simultaneous expression of PA-X and PB1-F2 enhanced the expression level of IL-18 and TNF-a during the early infection period, although individual expression of full-length PA-X or PB1-F2 could decrease the expression level of these two genes." (PMID 31552197, 2019). "IL-18 is believed to be directly involved in anti-infection and antitumour immunity and exerts negative feedback on IL-1β expression; on the other hand, IL-1β mainly induces inflammation injury by promoting the secretion of IFN-γ, IL-2 and GM-CSF by NK cells and T cells." (PMID 31827916, 2019). "NK cells stimulated by IL-12 or IL-18, secreted from dendritic cells and macrophages, produce several cytokines, principally IFN-γ, IL-1β, IL-8, IL-17A, and tumor necrosis factor alpha (TNF-α), which are involved in lung inflammatory processes and infection resistance." (PMID 31269777, 2019). "Similarly, infection of human corneal epithelial cells with virulent HSV-1 clinical isolate KOS79 induced a significant early activation of Caspase-1, IL-1β and IL-18." (PMID 31367214, 2019). "Finally, our results demonstrate that IL-18 does contribute in reducing parasite burden both at the site of infection and in peripheral tissue, but failed to rescue the survival of TLR11xCasp1/11-/- mice infected with the parasite." (PMID 31194844, 2019). "Furthermore, infection with virulent SIVmac251 strain directly upregulated the cytokine production (IFN-α/β, IL-12, IL-18) and led to the activation of natural killer (NK) cells which are one of the major antiviral innate immune cells and also act as a bridge to the adaptive system." (PMID 30568659, 2018). "The anti-infection defense of recombinant L. monocytogenes that enhanced the inflammasome activation is due to caspase-1-induced pyroptosis, but not due to the secretion of IL-1β and IL-18." (PMID 28468643, 2017). "Moreover, five days after infection with 108 CFU of STm, cytokine levels in pearl and WT MLN were similar (despite higher bacterial burden in pearl MLN), while serum Il-18 levels were higher in pearl than in WT mice correlating with the increased bacterial load." (PMID 29253868, 2017). "To investigate whether the NLRP7 inflammasome plays a role in the production of TNF-α and CCL3 besides IL-1β and IL-18, we silenced NLRP7 or ASC in THP-1 macrophages prior to infection, which significantly attenuated M. bovis-induced upregulation of TNF-α, CCL3 and IL-1β at the mRNA level." (PMID 27043315, 2016). "Interestingly, levels of IL-1β and IL-18 in the lung are markedly reduced in Nlrp3-/- mice with slower kinetics over the initial 6 days of infection with LVS or SchuS4 infection, but are not completely ablated." (PMID 27926940, 2016).
infection (continued). "However, IL-18 deficiency does not prevent Bgp1 expression, virus amplification and FGL2 accumulation in the liver following MHV-3 infection, and as the consequence, these mice stay high with fibrinogen deposition, liver damage and hepatocyte necrosis." (PMID 26367131, 2015). "With the progression of the infection a more equilibrated immunological balance is observed, with 6 genes showing significant transcription up-regulation: IFN-γ, IL-5, TNF-α, TGF-βR1, IL-21 and IL-23 and 4 extra genes showing significant down-regulation: DEFB1, CD163, IL-13 and IL-18." (PMID 26589145, 2015). "Thus, monocyte production of IL-18 was dependent on clathrin-mediated endocytosis, but not infection via entry receptors, consistent with an infection independent mechanism of inflammasome activation." (PMID 24788318, 2014). "Pre-infection plasma from the same individuals did not induce IL-18 or IL-1β." (PMID 24788318, 2014). "In addition, knockdown of Naip2, but not Naip5, reduced the release of IL-1β and IL-18 induced by Shigella infection at 1 or 2 hrs post-infection." (PMID 24516390, 2014). "Since IL-18 contributes to host defense against invading pathogens we could not exclude that elevation of IL-18 similarly to IL-1RA in examined children is an early marker of acute phase of infection." (PMID 24490166, 2013). "However, qRT-PCR analysis of IL-18 mRNA expression suggested that there was no significant increase in their levels even after 7 days of infection." (PMID 22393394, 2012). "Treatment of IL-12p40−/− with IL-18 bp also resulted in marked enhancement of viremia already at day 5 after infection, results which are similar to those obtained in IFN-γ−/− mice and substantially different from results observed at day 5 in IL-12p40−/− mice or mice treated with IL-18 bp alone." (PMID 22206036, 2011). "Indeed, IFN-γ production was not abolished in IL-12−/− or IL-18−/− mice and viral loads were only significantly different from WT at day 7 after infection." (PMID 22206036, 2011). "Therefore we assessed the contributions of IL-12 and IL-18 to the rapid activation of NK cells following infection with HSV-1 using mice lacking either IL-12p40 (B6.IL-12–/–) or IL-18 (B6.IL-18–/–)." (PMID 17407097, 2007). "Of note, infection with rCDC-9 P11 VP4_AA385 did not downregulate the pro-inflammatory response for selected cytokines (e.g., IL-1β, IL-18 MIP-1α) indicating that AA385 might be involved in reduced viral shedding in vivo but did not modulate inflammatory responses as seen with rCDC-9 P11 VP4_AA331." (PMID 41060027, 2025). "Similarly, while IL-18 supplementation did not affect the mucus barrier layer in the distal colon under baseline conditions, it did induce a significant increase in the mucus layer thickness of the Il22−/− mice during infection." (PMID 39428744, 2024). "The PBS group showed high levels of inflammatory cytokines including IL-6, IL-18, IL-12 p70, IFN-γ, and TNF-α as well as chemokine GMCSF, which may suggest enhanced vascular permeability and increased infiltration of innate immune cells in response to infection in unvaccinated animals." (PMID 38711520, 2024). "Moreover, IL-18 may also promote the secretion of other pro-inflammatory cytokines such as TNF-α, IL-1β, IL-8, and GM-CSF, which leads to an increase in the expansion, migration, and activation of neutrophils during infections." (PMID 39042701, 2024). "Other bacterial species relevant for colonizing the skin do not similarly activate immature pro-IL-18, so we hypothesize that this pool of cytokine is poised for activation to serve as an early sentinel for infection by potentially invasive pathogens that make use of proteolytic virulence factors." (PMID 37068092, 2023).
infection (continued). "We investigated whether infection with the P. aeruginosa strain, PAO1, induced expression of components of the NLRP3 inflammasome and found that a 6-h infection significantly increased expression of NLRP3, the adapter protein ASC, caspase-1, IL-1β, and IL-18 in BEAS-2B bronchial epithelial cells." (PMID 35215060, 2022). "Additionally, our pathway analysis revealed seven genes, IL-4, IFNγ, TLR4, CXCL8, IL-18, CSF2 and TNFα, are involved in the morphological and behavioral changes of macrophages, monocytes, granulocytes, and dendritic cells (DCs) and their recruitment into infection sites." (PMID 34753991, 2021). "As observed in the MDM model, infection with HSV-1/UV did not lead to more robust IL-18 production at these earlier time points, which supports the hypothesis that HSV-1 has evolved mechanisms that require de novo viral protein translation to inhibit inflammasome signaling." (PMID 32101570, 2020). "Therefore, upon infection with Gram-negative bacteria such as Salmonella typhimurium, the resulting production of IL-18 might participate in host defense against certain bacterial infections." (PMID 30717382, 2019). "A lack of IL-18/IL-18R signaling enhanced bacterial clearance, attenuated liver injury, decreased the production of pro-inflammatory cytokines (such as TNF-α), and decreased expansion of pathogenic TNF-producing CD8 T cells and NK cells following IOE infection." (PMID 31134081, 2019). "The increases in IL-1α observed later during infection in the spleens of BALB/c mice could indicate activation and secretion of IL-1α by inflammasome activation, though further data, such as caspase-1 activation and IL-18 expression would be required to validate this hypothesis." (PMID 30500862, 2018). "Similarly, IL-6 and IL-18 cytokines seem to have no role on infection outcome or to be markers of active disease or asymptomatic infection." (PMID 30237985, 2018). "However, in vitro infection or treatment of intestinal epithelial cells by T. gondii or LPS did not trigger an IL-1β or IL-18 response regardless of whether the P2X7R was present, suggesting that in epithelial cells P2X7R may have an alternative role." (PMID 27559003, 2017). "IL-18, in contrast to IL-15, does not influence the development or homeostasis of NK cells, but French and colleagues demonstrated that the IL-18 receptor is constitutively expressed on splenic NK cells and IL-18 contributes to NK cell proliferation during infections." (PMID 28904191, 2017). "As our data suggest that IL-18, in concert with γc cytokines, enhances adaptive and innate pathways of NK cell activation, we wanted to test whether ADCC could be augmented by very low levels of NK cell activating cytokines, as would be present at the site of infection." (PMID 27047490, 2016). "Our work identifies a key role of caspase-1 (not -11) mediated IL-18 production, IL-18-mediated accumulation of mature natural killer (NK) cells in the mucosa and suggests that NK-cell perforin is important for mounting gut inflammation within 12h of the infection." (PMID 27341123, 2016). "In contrast, IOE infection that fails to induce memory-like NK cells or provide a protective recall response to Ehrlichia promoted the production of inflammasome-dependent, pro-inflammatory cytokines, including IL-1α, IL-1β, and IL-18 (data not shown), and the immunosuppressive IL-10." (PMID 27092553, 2016). "The same group showed that mice deficient in both IL-1β /IL-18 are more susceptible than C57BL/6J mice, yet not as much as mice deficient in ASC or caspase-1, suggesting that other caspase-1-dependent pathways, most likely pyroptosis, significantly contributed to protection from infection." (PMID 25768794, 2015). "This could be an explanation for the phenotype observed in the Nlrp3−/− mice, which was comparable to WT mice, but not for the Asc−/− mice, as in both our infection models the IL-18 levels of Asc−/− mice remained below detection limit independent of the stage of infection." (PMID 25115174, 2014).